MGMT (O-6-methylguanine-DNA methyltransferase)
Diseases named in the same sentence as MGMT in open-access papers (continued):
Sharing a sentence is not in itself a finding about the gene and the disease.
cancer (continued). "Riluzole attenuates TMZ induced upregulation of MGMT and enriches the anti-cancer effect of TMZ in MGMT GBM specimens." (PMID 33096667, 2020). "The method we present offers a simple and effective method to measure the levels of active MGMT in cancer cells." (PMID 32075134, 2020). "Epigenetic silencing of DNA repair genes such as MLH1, MGMT, BRCA1, FANCF, CHFR and SLFN11 can lead to gene mutations and genomic instability in cancer cells." (PMID 32974031, 2020). "The cells with an intact MGMT gene exhibit drug resistance while therapeutic response to TMZ is improved in cancer cells with hypermethylated MGMT, which results in its repression resulting in the loss of MGMT protein expression." (PMID 33552543, 2020). "For some additional genes where methylation has been found as a cancer risk factor, MLH1 and MGMT, these revealed mean methylation levels of 6.4% and 18.6%, respectively." (PMID 32859265, 2020). "In the analysis of plasma samples from 48 NSCLC patients and 51 healthy controls, we found significant methylation profile differences between cancer and control groups at the p16, MGMT, and RASSF1 genes." (PMID 31903158, 2020). "CpG island hypermethylation in promoter region of TGSs as death-associated protein kinase (DAPK), O6-methylguanine DNA methyltransferase (MGMT) and runt-related transcription factor 3 (RUNX3) have been consistently observed in many human cancers." (PMID 32870234, 2020). "We also found copy number loss of cancer genes such as CCNE1, MAF, MAFB, MYC, ZNF479, and MGMT and copy number gain of FOXA2, CDH10, and GPC5 in at least two WDPM cases." (PMID 32545767, 2020). "At 5 weeks post-surgery, the expression of MGMT was lower in healthy sham rats compared to the untreated animals with implanted cancer cells." (PMID 33123485, 2020). "Recently, researchers found that MGMT-mediated the resistance to DNA alkylating agents in cancer cell is profoundly dependent on the DNA repair enzyme PARP." (PMID 33628188, 2020). "The activation of O6-methylguanine-methyltransferase (MGMT), a DNA repair enzyme in the cancer cells, impairs the activity of TMZ." (PMID 32971907, 2020). "In the CCLE public database, we analyzed the expression profile of MGMT in a series of cancer cell lines." (PMID 33033516, 2020). "Combination of temozolomide with PARP inhibitors (PARPi) in MGMT-positive cancer cells enhanced the anticancer effects." (PMID 33628188, 2020). "Because of its high prognostic and predictive relevance, assessment of the MGMT and hMLH1status as a prognosticator has become state-of-the-art in current and planned clinical trials of cancer." (PMID 31381583, 2019). "Although MGMT diminishes the effectiveness of cancer therapies, it also plays a critical role protecting normal tissues from DNA damage." (PMID 30811507, 2019). "Encouragingly, we encountered outstanding imidazotetrazine potency following AFt-encapsulation; surprisingly, AFt-TMZ overcame MGMT-mediated resistance, and demonstrated activity against MMR-deficient cancer cells." (PMID 35582280, 2019). "MGMT prevents cell killing by repairing O6-methylguanine (O6-MeG) cytotoxic DNA lesions induced by the cancer chemotherapy agents Temozolomide and Dacarbazine, and cytotoxic O6-chloroethylguanine lesions induced by cross-linking agents such as BCNU." (PMID 30811507, 2019). "1.MLH1 and MGMT, as well as other genes which are methylated in cancer tissues, should be assessed with respect to mosaic methylation in WBC or other types of normal tissue from healthy individuals." (PMID 31225507, 2019). "Many studies have confirmed that overexpression of the O6-methylguanine-DNA methyltransferase (MGMT) gene is an important mechanism of cancer resistance to chemotherapeutic drugs." (PMID 31320914, 2019).
cancer (continued). "The mechanisms contributing to the resistance to TMZ include the repair of DNA damage by enzyme O6-methylguanine-DNA-methyltransferase (MGMT) in cancer cells and/or an increased expression of ABC-type multidrug resistance (MDR) proteins." (PMID 31771235, 2019). "Conversely, inhibition of MGMT renders cancer cells sensitive to temozolomide, whereas MGMT promoter alkylation is a significant determinant in the sensitivity of drugs such as temozolomide." (PMID 31861764, 2019). "A clinical study published by Rong Z found that the methylation rate of MGMT genes in the plasma of cancer patients treated with dujieqing oral liquid is lower than those treated with chemotherapy alone." (PMID 31320914, 2019). "Since genetic variation, environmental exposures, and chemotherapy can each affect MGMT activity, methods that directly report MGMT function are best suited for studies measuring inter-individual differences in both normal tissues and cancer cells." (PMID 30811507, 2019). "The meta-analysis of p14, WIF1, PRDM2, p15 and MGMT gene methylation was performed between HBV-positive carcinoma tissues and HBV-negative carcinoma tissues." (PMID 31772678, 2019). "Previous studies have demonstrated that an inverse relationship existed between the MGMT contents and survival of malignant tumor patients treated with O6-guanine alkylating agents." (PMID 30404161, 2018). "We detected the MGMT methylation in 35 of 268 (13.1%) cancer-free women, in 29 of 295 (9.8%) delivering women, and in 37 of 302 (12.3%) newborns." (PMID 30049288, 2018). "The MGMT had a similar methylation status in cancer versus benign lesions and low malignant potential (LMP) samples (OR = 2.01, 95% CI = 0.67–6.04, p = .212; OR = 1.42, 95% CI = 0.46–4.40, p = .543; respectively)." (PMID 29195029, 2018). "The DNA repair enzyme O6-methylguanin-DNA-methltransferase (MGMT) is able to remove products of alkylating agent such as O6-meG and emerges as a central determinant of cancer resistance to temozolomide (TMZ)." (PMID 29426908, 2018). "Overall, PIK3CA mutations have been associated with KRAS mutant, MGMT methylated, and CIMP cancers; however, PIK3CA mutations in the catalytic exon 20 hotspot were found predominantly in BRAF mutant/MSI cancers." (PMID 30598662, 2018). "Intriguingly, the delivering women had 26% lower BRCA1 and MGMT methylation frequencies than those of the cancer-free female subjects." (PMID 30049288, 2018). "Cotreatment with honokiol and O6-benzylguanine, an MGMT inhibitor, caused effective cytotoxicity to those GBM cancer stem cells." (PMID 29614990, 2018). "To this end, we analyzed the MGMT promoter methylation in WBC using MSP assay in the same cohort of 865 cancer-free females." (PMID 30049288, 2018). "High levels of MGMT activity in cancer cells lead to a phenotype that is resistant to alkylating agents and MGMT is likely to play an important role in therapeutic failure." (PMID 29337870, 2018). "In the present study, we aimed at determining the potential role of rs12917 polymorphism of the O-6-methylguanine-DNA methyltransferase (MGMT) gene in the occurrence of cancer." (PMID 30232235, 2018). "As for CRC, the significantly higher APC, FOXA1, RARβ2, RASSF1A, SCGB3A1, SEPT9 and SOX17 methylation levels in cancer patients are in line with previous publications, although divergent results have been reported for MGMT." (PMID 30261643, 2018). "The importance of epigenetic silencing in cancer etiology is similarly illustrated by the example of MGMT promoter methylation, which can lead to development of G→A transition mutations resulting from unrepaired O6-methylguanine adducts." (PMID 30120226, 2018). "In this study, we investigated the prevalence of BRCA1 and MGMT promoter methylations in white blood cells (WBC) from cancer-free women and newborn females." (PMID 30049288, 2018).
cancer (continued). "We have previously shown that the MGMT gene is methylated in WBC of cancer-free BRCA1 methylation carriers." (PMID 30049288, 2018). "Since Temozolomide is more effective in treating cancers with low MGMT levels we tested the effect of co-treatment with the MGMT inhibitor Lomeguatrib." (PMID 30304478, 2018). "Further studies conducted on large series of carcinomas, and more importantly with distinction of the different histotypes, are required to determine the precise role of MGMT methylation in ovarian tumorigenesis and outcome." (PMID 29882921, 2018). "MGMT is a DNA-repair protein that it can counter the effect of temozolomide by removing alkyl groups from guanine, allowing cancer cells to be resistant to temozolomide chemotherapy." (PMID 28881684, 2017). "We used MGMT as the prototype to demonstrate the proof of concept for modulating a cancer-specific protein; this technique can potentially be used to target other proteins." (PMID 28752860, 2017). "Acetaldehyde interferes with DNA synthesis and repair causing inhibition in the O6-methylguanine-DNA methyltransferase (MGMT) activity, which can be involved in cancer pathogenesis." (PMID 26886278, 2017). "According to the importance of SFRP2 and MGMT role in cancer progression, promoter methylation of these two genes was investigated in HCT 116 treated with CPUK02." (PMID 28090275, 2017). "In this study, we have investigated glucose-conjugated MGMT inhibitors as a targeting strategy for MGMT positive cancers, which are inevitably resistant to alkylating drug-based therapies." (PMID 29066805, 2017). "In cancer, MGMT epigenetic silencing confers a poor prognosis, thus it is also an indicator of enhanced responsiveness to treatment with alkylating agents." (PMID 27776349, 2017). "Meanwhile, the up-regulation of O-6-methylguanine-DNA methyltransferase (MGMT) in the cells after the treatment of TMZ makes the cancer resistant to it." (PMID 28477008, 2017). "The DNA repair protein O6-methylguanine-DNA-methyltransferase (MGMT) is a key determinant of cancer resistance." (PMID 29066805, 2017). "The difference between normal and abnormal cells in MGMT gene position and its colocalization with euchromatin domains suggest a connection between gene regulation, nuclear position, and cancer-related 3D nuclear architecture." (PMID 27503568, 2016). "A sex-based subgroup analysis revealed that MLH1 methylation in the cancer tissues of the lower-third stomach was typical of the female population (p = 0.01), whereas MGMT methylation was only statistically significant in the male group (p = 0.03)." (PMID 26810771, 2016). "Alkylating drugs are therefore more effective in cancers that have low levels of MGMT, and for this reason, MGMT itself has become attractive as a drug target, since depleting its activity enhances the potency of alkylating drugs." (PMID 27035132, 2016). "The silencing of the tumor suppressor gene O-6-methylguanine-DNA methyltransferase (MGMT) by promoter methylation commonly occurs in human cancers." (PMID 27824946, 2016). "In this study we provide an alternative strategy for targeting chemoresistant cancers by modulating MGMT protein expression through canonical Wnt cascade inhibition." (PMID 26603103, 2015).
cancer (continued). "To investigate if Wnt signalling is involved in the regulation of MGMT expression, we genetically blocked the activity of Wnt signalling using shRNA that render the Wnt signalling activity within cancer cells." (PMID 26603103, 2015). "We show that activation of the canonical Wnt/β-catenin signalling cascade induce MGMT expression, and that inhibition of Wnt signalling augment the effects of alkylating drugs and restore chemosensitivity in different cancers." (PMID 26603103, 2015). "Here we show a significant correlation between Wnt signalling and MGMT expression in cancers with different origin and confirm the findings by bioinformatic analysis and immunofluorescence." (PMID 26603103, 2015). "Epigenetic modifications of MGMT gene have been found to play a relevant role in MGMT expression in the context of cancer." (PMID 26035292, 2015). "MGMT expression protects normal cells from carcinogens; however, it can also protect cancer cells from chemotherapeutic alkylating agents." (PMID 26347581, 2015). "Together these results suggest that targeting β-catenin restores temozolomide chemosensitivity in cancer cells expressing MGMT." (PMID 26603103, 2015). "The high expression of the DNA repair enzyme O6-methylguanine DNA methyltransferase (MGMT) often confers resistance to chemotherapy in several cancers." (PMID 26603103, 2015). "Knockdown of MGMT in the ERp29-transfected cancer cells increased radiosensitivity, leading to a decreased post-irradiation survival." (PMID 26420420, 2015). "EGCG is active against many types of cancer cells, demethylates and reactivates several genes involved in cancer like p16, RARβ, MGMT, hMLH1, and GSTP1." (PMID 26339624, 2015). "MGMT expression in cancer cells can inhibit the success of chemotherapy treatment with alkylating agents, which work by triggering DNA methylation." (PMID 27231557, 2014). "Normal cells all have MGMT expression, while some malignant tumors will lose MGMT expression which will induce the damage of DNA repair and the carcinogenesis of cells." (PMID 24502441, 2014). "It should be noted that a large number of cancer cells display high constitutive activity of NF-kappaB and consequently high expression levels of MGMT." (PMID 25460932, 2014). "Mehtylation rate in MGMT gene promoter of cancer tissue in NSCLC patients was much higher than that in normal lung tissue and plasma, which showed a close association between NSCLC cancer and MGMT gene promoter methylation." (PMID 25130966, 2014). "To summarize, hypermethylation-induced transcriptional silencing of MGMT and p16 genes in both oral precancer and cancer distinctly separate from normal oral mucosa suggests an important role of these changes in progression of premalignant state to malignancy." (PMID 24991542, 2014). "Hypermethylation-induced transcriptional silencing of MGMT and p16 genes in both precancer and cancer suggests important role of these changes in progression of premalignant state to malignancy." (PMID 24991542, 2014). "The DNA repair enzyme, O6-methylguanine DNA methyltransferase (MGMT), which functions in the resistance of cancers to TMZ, can repair this damage." (PMID 25295108, 2014). "The downside is that MGMT with the same mechanism can protect cancer cells from alkylating chemotherapeutic agents." (PMID 24151575, 2013). "For example, TS genes involved in DNA repair such as BRCA1, MLH1 and MGMT show promoter hypermethylation in human cancers." (PMID 23472065, 2013). "The DNA hypermethylation of P16, MGMT and hMLH1 in cancer tissue and paracancerous normal tissue was shown in Table-II." (PMID 24550949, 2013). "MGMT expression was significantly lower in serrated lesion tissues compared with that of complicating cancer tissues (P=0.022), control cancer tissues (P=0.002) and normal colorectal mucosal tissues (P=0.003)." (PMID 24223631, 2013).
cancer (continued). "Due to the limited number of the cases included in the present study, further studies are needed to investigate the expression of MGMT in cancer tissues and HPs." (PMID 24223631, 2013). "Immunohistochemical investigation showed a positive expression of MGMT in cancer tissues with a reduced expression of MGMT in HPs." (PMID 24223631, 2013). "The proportion of DNA hypermethylation in P16, MGMT and hMLH1 in cancer tissues were significantly higher than remote normal-appearing tissues." (PMID 24550949, 2013). "An increase in MGMT gene promoter methylation, which blocks MGMT protein expression, prolongs cancer patient survival." (PMID 23459853, 2013). "Silencing of the DNA repair gene O6-methylguanine-DNA methyltransferase (MGMT) by methylation of its promoter region is an early event that occurs in various cancers." (PMID 22938091, 2012). "MGMT is a TSG, located at 10q, playing vital roles in preventing induction of mutations and cancer related to alkylating agents." (PMID 22246327, 2012). "O6-methylguanine DNA methyltransferase (MGMT) is a DNA repair enzyme that is believed to induce cancer cell resistance to O6-alkylating agents, for example, TMZ." (PMID 22973169, 2012). "MAM forms DNA lesions – repaired by O6-methylguanine methyltransferase (MGMT) – that perturb mouse brain development and induce malignant tumors in peripheral organs." (PMID 23060898, 2012). "In another study, participation of DNA methylation in five CIMP-specific gene promoters, including MGMT, was also evaluated in six synchronous carcinoma pairs." (PMID 20098741, 2010). "Epigenetic changes in cancer, more recently referred to as the cancer epigenome, have traditionally been evaluated by measuring the status of CpG island cytosine methylation of a particular gene such as MGMT using Methylation-Specific PCR (MSP-PCR)." (PMID 19807915, 2009). "Epigenetic changes in cancer have traditionally been evaluated by measuring the status of CpG island cytosine methylation of a particular gene, such as MGMT." (PMID 19807915, 2009). "In all except two of the cancer specimens, MGMT promoter methylation revealed identical results by MS-MLPA and Ms-SNuPE." (PMID 17971771, 2007). "Current phase I studies are investigating the dose of PaTrin-2 that is necessary for complete inactivation of MGMT in patients with a variety of cancer types, prior to phase II studies." (PMID 16278661, 2005). "There are reports in the literature regarding the promoter hypermethylation and gene silencing of MGMT in many cancers." (PMID 14970867, 2004). "A clinical trial involving transduction of G156A MGMT into CD34+ cells of patients with cancer has been approved." (PMID 14562026, 2003). "Integrating MGMT modulation with immunotherapy could pave the way for more personalized and effective cancer treatments." (PMID 40895460, 2025). "In addition, a national cancer database study of bGBM showed that MGMT promoter methylation, a known favorable prognostic and predictive factor in GBM, was in fact more prevalent in bGBM patients (47.1% vs. 40.2%)." (PMID 40338381, 2025). "While a potential role for MGMT constitutional epimutations to cancer risk has not been prospectively evaluated, MGMT epimutations are strongly associated with the alternative allele of rs16906252." (PMID 39980037, 2025). "MGMT status varies across different cancers, influencing therapeutic outcomes and survival." (PMID 40895460, 2025). "Furthermore, the strategic combination of PARP and MGMT inhibitors is being explored in various cancers that exhibit similar resistance mechanisms." (PMID 40895460, 2025). "The efficacy of these drugs can be compromised by the presence of MGMT in cancer cells." (PMID 40183077, 2025).